VASH2 (vasohibin 2)
Diseases named in the same sentence as VASH2 in open-access papers (continued):
Sharing a sentence is not in itself a finding about the gene and the disease.
tumor (32 papers, 2013 to 2026). "In contrast to plasma, which measures systemic levels of VASH1, VASH2, and NO, circulating WBCs actively contribute to tumor-associated immune and angiogenic activities, expressing these markers in direct response to tumor signals." (PMID 40483461, 2025). "VASH2 is abundantly expressed in ovarian cell carcinoma, where it stimulates tumor angiogenesis and its knockdown causes tumor regression." (PMID 37245177, 2023). "Over-expression of a paralogue, Vasohibin-2 (VASH2), is associated with diverse tumours, with major roles to angiogenesis, malignant transformation, and metastasis." (PMID 26794318, 2016). "Similarly, high VASH-2 expression is associated with poor prognosis and tumor growth in esophagus squamous cell carcinoma." (PMID 40497943, 2025). "In contrast to VASH1, which is closely linked to tumor progression and angiogenesis, VASH2 may play a more restricted or context-dependent role within the HNSCC tumor microenvironment." (PMID 40483461, 2025). "VASH2 expression was associated with higher tumor grade and more vessel cancerous embolus." (PMID 28327155, 2017). "Interestingly, we discovered in the present study that, in addition to high VASH2 expression in tissues, the protein level of VASH2 gradually increased with decreased degree of tumor differentiation (P<0.01), which is reportedly associated with the curative effect of chemotherapeutic drugs." (PMID 24595063, 2014). "This reduction in H3K18 lactylation attenuates the transcriptional activation of the downstream oncogenes IL1RAP and VASH2, thereby ultimately suppressing tumor malignancy in BC." (PMID 41757512, 2026). "VASH1 and VASH2, as regulators of angiogenesis, exert opposing effects, while NO influences vascular dynamics, collectively shaping the tumor microenvironment." (PMID 40483461, 2025). "Assessing angiogenesis-regulating markers, including VASH1, VASH2, and iNOS, in circulating WBCs provides deeper insights into the tumor microenvironment and immune response in HNSCC, surpassing the limitations of plasma measurements alone." (PMID 40483461, 2025). "Second, the distinct roles of VASH1 and VASH2 in the tumor microenvironment suggest avenues for investigating their interactions with other angiogenic factors, such as VEGF, and immune checkpoint pathways to optimize targeted therapies and immunotherapies." (PMID 40483461, 2025). "Further research is essential to elucidate the specific role of VASH2 and its interactions with other angiogenic factors, providing deeper insights into its implications for tumor behavior and vascular remodeling in HNSCC." (PMID 40483461, 2025). "Blocking the tubulin carboxypeptidase (TCP) activity of VASH2 inhibited the xenograft tumor growth and improved the treatment efficacy of paclitaxel in vivo." (PMID 39443476, 2024). "Studies have reported that VASH2 is able to promote tumor growth by accelerating angiogenesis in various cancers, including breast cancer, liver cancer, ovarian cancer, and gastrointestinal cancer." (PMID 39443476, 2024). "VASH2 has been considered an angiogenic factor which promotes tumor progression by accelerating tumor angiogenesis in various cancers, but other roles of VASH2 in tumor cells are poorly understood." (PMID 39443476, 2024). "The silence of KIF3C attenuated VASH2-caused chemoresistance in LUSC cells and decreased H520VASH2-xenograft tumor growth." (PMID 39443476, 2024). "One study showed that the knockdown of VASH2 significantly increased the chemosensitivity of tumor cells to paclitaxel PTX22." (PMID 37821528, 2023). "Untreated tumors showed VASH1 mainly close to vascular structures in the extracellular matrix, whereas VASH2 was found within tumor cells." (PMID 35145607, 2022). "It is an exciting characteristic and suggests VASH2 as an inhibitor of angiogenic development mediated by the tumor cell." (PMID 35145607, 2022).
tumor (continued). "The greater specificity of VASH2 than 1 in tumor cells suggests that VASH2 is a suitable target for blocking angiogenesis in CC." (PMID 35145607, 2022). "Peritoneal injection of anti-VASH2 neutralizing antibodies inhibited tumor growth and angiogenesis in a mouse xenograft model of human cancer cells." (PMID 35054524, 2022). "In turn, VASH2 was found in the cytoplasm of tumor cells and was downregulated in comparison to cancer cells from control mice." (PMID 35145607, 2022). "Yuzhi and colleagues indicated that vasohibin-2 (VASH2) involved in the promotion of angiogenesis in tumor tissues is regulated post-transcriptionally by miR-200b/c in vascular endothelial cells of epiretinal fibrovascular membranes from PDR patients." (PMID 33995938, 2021). "On the other hand, VASH2, which appears to play an important role in cancer cell proliferation, promotes tumor angiogenesis and growth." (PMID 33114575, 2020). "Our findings indicated that in HCC, VASH2 is regulated by miR-200a/b/c to promote tumor growth, invasion, metastasis and resistance to chemotherapy by inducing EMT in tumor cells." (PMID 25269476, 2014). "Third, VASH2 expressed in the adenocarcinoma cells promoted tumor growth and tumor angiogenesis in ApcMin/+ mice." (PMID 24885408, 2014). "Here, we showed for the first time that VASH2 was preferentially expressed in HCC tumor cells and tissues." (PMID 25269476, 2014). "We sought to characterize microvascular changes and tumor development in the intestinal tract of ApcMin/+ mice and ApcMin/+/Vash2-/- mice." (PMID 24885408, 2014). "In contrast, VASH2 interference attenuates the tumor size and suppresses angiogenesis in a subcutaneous tumorigenesis model." (PMID 25269476, 2014). "To understand the role of VASH2 in tumor vessels, we compared the histopathological abnormalities of tumor vessels in ApcMin/+ mice and ApcMin/+/Vash2-/- mice." (PMID 24885408, 2014). "We found that VASH2 knockdown markedly limited the tumor growth and enhanced the CDDP toxicity and apoptosis of tumor cells." (PMID 24595063, 2014). "In our studies, by inducing EMT in HCC, VASH2 was shown to promote tumor invasion, metastasis and drug resistance as well as to increase the SP cell proportion." (PMID 25269476, 2014). "In contrast, some tumor lesions in ApcMin/+/Vash2-/- mice were less vascularized than hyperplastic lesions in the polyps." (PMID 24885408, 2014). "To date, there are a limited number of studies available in the literature concerning the correlation between VASH2 and tumor angiogenesis." (PMID 23426782, 2013). "Recently, VASH2 has been demonstrated to be expressed in several types of cancer in which it promotes tumor development through angiogenesis." (PMID 23426782, 2013). "In contrast to VASH-1, VASH-2 has been shown to promote tumor growth." (PMID 40497943, 2025). "Alternatively, VASH2 may predominantly influence early tumor development, with its expression stabilizing in advanced HNSCC, resulting in minimal responsiveness to surgical intervention." (PMID 40483461, 2025). "However, besides promoting tumor angiogenesis and lymphangiogenesis, other roles of VASH2 in tumor progression are poorly studied." (PMID 39443476, 2024). "Hence, it is important to explore the molecular mechanism of VASH2-induced tubulin detyrosination in tumor development." (PMID 39443476, 2024). "Distinct from VASH1, VASH2 was also found in the tumor cells." (PMID 35145607, 2022). "Although higher levels of VASH1 are associated with poorer prognosis for some cancers, this may be due to increased VASH1 feedback in vivo and inhibition of angiogenesis factors (VEGF, FGF-2, and VASH2) in the tumor microenvironment." (PMID 36504559, 2022). "In contrast, VASH2 occurs mainly in cancer cells and has a stimulating effect on tumor growth." (PMID 35054524, 2022).
tumor (continued). "VASH2 is expressed in CC cells and accelerates tumor angiogenesis and progression." (PMID 35145607, 2022). "VASH2 is expressed by various cancer cells and accelerates tumor angiogenesis and progression." (PMID 33710778, 2021). "VASH2 has multiple functions in tumor cells and the tumor microenvironment." (PMID 33710778, 2021). "Firstly, the cell cycle delay observed upon VASH1/2 and VASH2 deletion might unveil the importance of VASH2 for proper cancer cell proliferation and tumor development." (PMID 33114575, 2020). "In addition, recent evidence suggested that VASH2 not only promotes tumor angiogenesis but also induces EMT in cancer cells, thus enhancing the malignant behavior." (PMID 32604722, 2020). "Vasohibin-2 (VASH2) is a novel proangiogenic factor that promotes tumor angiogenesis." (PMID 32604722, 2020). "Our results showed that all the tumor cell lines also expressed VASH2." (PMID 25797264, 2015). "Recent studies have shown that VASH2 also plays a critical role in tumor pathogenesis." (PMID 25797264, 2015). "However, tumor blood vessels in ApcMin/+/Vash2-/- mice had more pericyte coverage compared with ApcMin/+ mice." (PMID 24885408, 2014). "Its role in tumor angiogenesis is unknown, but it is likely that VASH2 functions via mechanisms that are distinct from those of VEGF." (PMID 24885408, 2014). "We propose that VASH2 may modulate the onset of tumors in the gastrointestinal tract by regulating tumor angiogenesis." (PMID 24885408, 2014). "Collectively, our data suggests that VASH2 is responsible for promoting tumor angiogenesis in HCC." (PMID 25269476, 2014). "Because inhibition of VASH2 normalized abnormal tumor vessels in adenocarcinoma, VASH2 may be an important therapeutic target in the treatment of human cancers." (PMID 24885408, 2014). "In the contrary, VASH2 knockdown orthotopic reduced the tumor size in vivo." (PMID 25269476, 2014). "Further delineation of the role of VASH2 in tumor angiogenesis may lead to novel strategies in anti-tumor therapy." (PMID 24885408, 2014). "Overexpressed VASH2 significantly contributes to tumor growth in vivo and to tumor angiogenesis." (PMID 25269476, 2014). "Here, we further investigated the role of VASH2 in HCC tumor progression." (PMID 25269476, 2014). "In addition to, VASH2 expression gradually increased with decreased degree of tumor differentiation." (PMID 24595063, 2014). "Furthermore, in gastrointestinal tumors of ApcMin/+/Vash2-/- mice, the number of small intestinal polyps was significantly reduced, pericyte coverage of tumor vessels was increased, and tumor lesions were less vascularized than hyperplasia lesions." (PMID 24885408, 2014). "Our results indicate a novel role for VASH2 in tumor angiogenesis as an index of malignant transformation and suggest that VASH2 may be a novel target for anti-angiogenic agents in cancer therapy." (PMID 24885408, 2014). "Moreover, paclitaxel treatment efficacy on LUSC was remarkably improved in combination with EpoY in vivo, which suggested that blocking TCP activity of VASH2 could inhibit LUSC tumor growth and increase the sensitivity of chemotherapeutic drugs." (PMID 39443476, 2024). "In addition, the expression of VASH2 was detected in tumor cells from adenocarcinomas." (PMID 24885408, 2014). "However, it is not known if there are differences in VASH2 expression between tumor cells and tumor-associated ECs." (PMID 24885408, 2014). "Thus, to clarify the function of endogenous VASH2, we examined whether tumor growth and tumor angiogenesis were altered in Vash2-/- mice." (PMID 24885408, 2014). "After tumor resection, plasma VASH1 levels were significantly downregulated (2233 ± 1464 pg·mL−1 vs. 2425 ± 1493 pg·mL−1, p = 0.0085), while plasma VASH2 levels remained unchanged in HNSCC patients." (PMID 40483461, 2025).
tumor (continued). "To further evaluate the efficacy of the combined treatment with paclitaxel and the TCP inhibitor against VASH2-induced paclitaxel resistance in vivo, we established a BALB/c-nu xenograft model using H520VASH2 cells and analyzed the tumor control rate." (PMID 39443476, 2024). "Taken together, these findings illustrated that KIF3C knockdown blocked the VASH2-induced enhancement of EGFR endosomal recycling and rescued LUSC tumor progression and chemoresistance." (PMID 39443476, 2024). "VASH1 and VASH2 have been reported to function differently, with VASH1 inhibiting angiogenesis and tumor metastasis, whereas VASH2 promotes angiogenesis and tumor progression." (PMID 39443476, 2024). "Q3G impaired tumor growth and vascularization, upregulated VASH1, and downregulated VASH2 in comparison to untreated animals." (PMID 35145607, 2022). "Thus, the targeting of VASH2 may offer safer and more tumor‐specific favorable outcomes." (PMID 33710778, 2021). "VASH2 effects both PDA cells and the tumor microenvironment by promoting tubulin detyrosination-lead tumor cell migration, tumor angiogenesis, as well as induction of myeloid derived suppressor cells." (PMID 32780245, 2020). "Vasohibin-2 (VASH2) has been identified as an endogenous and vascular endothelial growth factor (VEGF)-independent angiogenic factor that is highly expressed in tumor cells." (PMID 24885408, 2014). "In contrast to VASH1, VASH2 not only promotes angiogenesis, but also highly expresses in HCC cells and tissues and promotes HCC cell proliferation and tumor growth." (PMID 24595063, 2014). "Overexpression of VASH2 in HCC induced EMT and thus promoted tumor invasion, metastasis and drug resistance as well as increased the proportion of SP cells." (PMID 25269476, 2014). "Therefore, VASH2 may possess other tumor-promoting functions, such as invasion and migration." (PMID 23426782, 2013). "The interplay between VASH1 and VASH2 underscores their potential as prognostic biomarkers, with VASH1 levels in circulating white blood cells (WBCs) possibly indicating anti-angiogenic capacity, tumor behavior, and response to therapies." (PMID 40483461, 2025). "Our study revealed significantly higher VASH1 levels in HNSCC patients compared to non-cancer controls, with no notable difference in VASH2 levels, reflecting their distinct roles in the tumor microenvironment." (PMID 40483461, 2025). "Additionally, we investigated the influence of the tumor process on these markers by comparing their baseline levels in plasma (VASH1, VASH2, NO) and circulating WBCs (VASH1, VASH2, iNOS) between HNSCC patients and non-cancer controls." (PMID 40483461, 2025). "Immunohistochemistry of tumor sections showed that the use of EpoY decreased the level of deY-tubulin without affecting the expression of VASH2." (PMID 39443476, 2024). "Similarly, Vasohibin 2 (VASH2) protein suppresses pancreatic CSCs through decreasing SMO and Gli1/2, while also functioning as a tumor promoter, stimulating resistance to doxorubicin (DOX) upregulating pancreatic CSCs via the Hh and Notch pathways." (PMID 37305676, 2023). "A previous study also showed that VASH2‐induced tumor angiogenesis and its antitumor activity were inhibited by a neutralizing anti‐VASH2 monoclonal antibody, similar to bevacizumab, without obvious side effects." (PMID 33710778, 2021). "Additionally, VASH2, an endogenous angiogenesis inhibitive factor, was downregulated in IVL tumor samples when compared to LM tumors." (PMID 32372565, 2020). "Additionally, miR-29a targets the 3'UTR region of vasohibin 2 (VASH2), which was identified as an angiogenic factor in tumor tissue." (PMID 28187439, 2017). "In addition to finding the expression level of VASH2 higher in HCC tumors than in normal livers, we also observed that it gradually increased with decreased degree of tumor differentiation." (PMID 24595063, 2014).
tumor (continued). "Although knockdown of VASH2 with stable transfection of shRNA had little effect on the proliferation of HEC50B cells in vitro, knockdown in an in vivo murine xenograft model inhibited tumor growth by decreasing tumor angiogenesis." (PMID 23426782, 2013). "In contrast, VASH2, expressed in cancer cells or infiltrating mononuclear cells, may not be consistently elevated due to tumor heterogeneity or variable immune cell infiltration." (PMID 40483461, 2025). "The results showed that the expression of SH2D2A and GATA2 were upregulated (P = .0067 and P = .6021, respectively), while CXCL8, LIF, and VASH2 were downregulated in IVL tumor samples compared to nontumor tissue (P = .9281, P = .5406 and P = .0625, respectively)." (PMID 32372565, 2020). "Although VASH1 and VASH2 have opposite effects on tumor angiogenesis, they may not always exert opposite functions in various pathological processes." (PMID 32604722, 2020). "K19 may enhance tumour angiogenesis by regulating FGFR1, VASH1, and VASH2 in HCC." (PMID 27863477, 2016). "However, prior studies have not explored whether tumor resection specifically affects VASH1 or VASH2 concentrations in cancer patients." (PMID 40483461, 2025). "Importantly, EpoY reduced VASH2 secretion into the supernatants in a dose-dependent manner, suggesting that TCP inhibitor may inhibit the pro-angiogenic effects of VASH2 in the tumor microenvironment by reducing the secretion of soluble VASH2 in LUSC cells." (PMID 39443476, 2024). "Unlike VEGF and other angiogenic factors, VASH2 is an endogenous and VEGF-independent angiogenic factor that is highly expressed in bone marrow-derived mononuclear cells and tumor cells, but only weakly expressed in ECs." (PMID 24885408, 2014).